STAT3 (signal transducer and activator of transcription 3)
Diseases named in the same sentence as STAT3 in open-access papers (continued):
Sharing a sentence is not in itself a finding about the gene and the disease.
tumor (continued). "In addition to Jak/Stat3, PI3k/Akt and Erk signaling pathways have been reported to have interacted with GM-CSF in regulating tumor cell proliferation and migration." (PMID 35600882, 2022). "Therefore, the STAT3 multitargeting strategy using mc-3Stat3 treatment significantly improved mc-1Stat3 antitumoral activity by nearly 50% and 75% in reducing tumor growth and lung metastasis, respectively." (PMID 35847174, 2022). "Downstream in the GH/IGF1 signaling there is an strong analogy between inhibiting the GHR in mice with BM001 and the inhibitory effect of the small molecule S3I-201 on STAT3 with the same cancer cells: Both inhibitors resulted in tumor regression of MM231 xenografted mice." (PMID 35966052, 2022). "They suggested that targeting STAT3 in combination with inducers of the apoptosis pathway may be a potential novel strategy for treating tumor cells." (PMID 35402265, 2022). "STAT3 proteins play an important role in the survival and proliferation of tumor cells." (PMID 36080130, 2022). "Interestingly, the selective JAK2/STAT3 inhibitor JSI-I24 can revert the tumor-derived factors that block DC differentiation and maturation inducing the upregulation of MHC class II and costimulatory molecules." (PMID 36230990, 2022). "It has been shown that VEGF causes an increase in MDSCs and suppresses anti-tumor immune responses because VEGF expression over-activates Janus Kinases 2/Signal Transducer and Activator of Transcription 3 (Jak2/STAT3) signaling, leading to aberrant myeloid differentiation in tumors." (PMID 36569915, 2022). "Based on these findings, we hypothesize that NF-κB inhibition by the TLM_CFM-F_OSM combination regulates STAT3 expression and thus tumor growth and metastasis in H1975 tumors." (PMID 35745729, 2022). "In tissue array studies, enhanced S1PR1 co-localising with STAT3 was commonly seen in higher-grade GC tumours; GC patients with high S1PR1-STAT3 expression responded poorly to chemotherapy drugs and blocking S1PR1-STAT3 signalling re-sensitised drug resistance in GC cells." (PMID 35158806, 2022). "However, established opinions on the tumor-promoting effects of STAT3 have been frequently challenged." (PMID 35463085, 2022). "Therapeutic strategies to mitigate neutrophil-CAF-tumor cell IL-1β/IL-6/STAT-3 signaling during NAC may improve pathologic responses and/or survival in PDAC." (PMID 36107485, 2022). "In addition to influencing the immune infiltration of tumors, CCR5 can promote invasion and tumor cell migration by activating JAK/STAT3, MAPK/ERK, and PI3K/Akt signaling pathways." (PMID 35865011, 2022). "Excessive activation of STAT3 has been observed in a variety of tumor cells and tissues." (PMID 35559037, 2022). "Aberrantly active STAT3 promotes cancer progression in part by dysregulation of gene expression to support uncontrolled cell growth and survival, angiogenesis, and metastasis and by suppressing tumor immune surveillance." (PMID 36473850, 2022). "Thus, the significant reduction of tumor formation after STAT3 inhibitor treatment indicates the essential role of STAT3 in Shh MB development." (PMID 34482626, 2022). "In addition, PD-L1 expression in CRC specimens is positively correlated with FGFR2 expression, which promotes PD-L1 expression in CRC by activating the JAK/STAT3 signaling pathway, which further promotes T cell apoptosis and leads to tumor immunosuppression." (PMID 35740594, 2022). "Further, inflammation is associated with tumor cell proliferation, survival, metastasis, angiogenesis, and chemoresistance and may also affect the efficacy of CRC therapies, including STAT3 inhibitors." (PMID 36499154, 2022). "STAT3 facilitates cancer cell proliferation and survival, tumor spheroid formation, and metastasis." (PMID 35211652, 2022).
tumor (continued). "PTEN knock-down decreases the ability of T cells to kill tumour cells through the indirect activation of STAT3, a transcription factor that is a key signalling node and a regulator of the critical hallmarks of cancer, tumour angiogenesis, resistance to apoptosis, metastasis, and immune evasion." (PMID 36230538, 2022). "In addition, PD-L1 on neutrophils is upregulated by gastric cancer cell-derived EVs, activated by HMGB1 via phosphorylating STAT3 and downstream molecules, which suppresses T-cell immunity to have a pro-tumor influence." (PMID 36405712, 2022). "Importantly, treatment with a STAT3 inhibitor significantly blocks tumor formation in a murine transgenic model of Shh‐driven MB." (PMID 34482626, 2022). "Moreover, nuclear cooperative translocation of HIF-1α and p-STAT3 has been observed in the tumor microenvironment." (PMID 36496973, 2022). "Based on the current evidence, STAT3 inhibition might not only impair tumor cell survival but also enhance their recognition by NK cells." (PMID 35865518, 2022). "However, in humans and mice, it has been demonstrated that hypoxic tumor micro-environments decrease the expression of STAT3 in tumor-infiltrating MDSCs by triggering CD45 phosphatase." (PMID 35456003, 2022). "STAT3 has been reported to be regulated by tumor suppressor miRNAs in numerous cancers." (PMID 36295083, 2022). "Interestingly, STAT3 can also take part in a tumor-suppressive pathway, LIFRβ (leukemia inhibitory factor receptor β)/STAT3 pathway." (PMID 36338770, 2022). "It enhanced chemosensitivity of tumor cells to doxorubicin through inhibition of STAT3 activity." (PMID 36319798, 2022). "The activator of transcription 3 (STAT3) is a key regulator of tumor-induced immune suppression." (PMID 34072037, 2021). "Since we have previously shown that the PEBP-inhibited PI3K/AKT pathway was also accompanied by a decrease in STAT3 activation, it could be argued that regulation of miR-145 will potentially lead to tumor control and regression." (PMID 34299605, 2021). "Taken together, it is plausible to speculate that nifuroxazide treatment decreases tumor angiogenesis via the inhibition of the IL-6/Jak2/STAT3 pathway." (PMID 34833950, 2021). "Additionally, the expression analysis revealed a correlation between IL-6 and p-STAT3 expression in tumor tissues." (PMID 34657635, 2021). "Alternatively, the persistent activation of STAT3, has been shown to promote tumorigenesis through suppression of anti-tumor immune responses and through stimulation of proliferation, survival, and invasion of tumor cells." (PMID 34483843, 2021). "Therefore, B7-H6 can increase tumorigenesis in tumor cells through the activation of a transcription factor such as the STAT3 signaling pathway." (PMID 34639059, 2021). "Besides, the loss of LINC00852 significantly increased miR-140-3p expression, reduced AGTR1 expression and inhibited the activation of MEK/ERK/STAT3 pathway in tumor tissues from SKOV-3 xenograft mice." (PMID 34496800, 2021). "The receptor tyrosine kinase c-Met induces tumor development by activating multiple downstream molecules, including the oncogenic transcription factor signal transducer and activator of transcription 3 (STAT3)." (PMID 33801016, 2021). "Note that noncoding RNAs also regulate tumor progression by regulating STAT3." (PMID 34365889, 2021). "As a major source of CCL2, CAFs might induce MDSCs to migrate into tumor sites by stimulating the STAT3 signaling pathway." (PMID 34635121, 2021).
tumor (continued). "The experimental results verify our above analysis; that is, overexpression of LTF in PRAD cells can affect the expression of STAT3 through JAK/STAT pathway to reduce tumor-derived GM-CSF secretion and then interfere with the local immunosuppressive function of MDSCs." (PMID 34868909, 2021). "In an orthotopic glioblastoma (GL-26) model, intranasally administered EL-4 (murine lymphoblast) EVs loaded with JSI124 (STAT3 inhibitor) were shown to increase tumor apoptosis, survival, and concomitant reduction of tumor, as well as decrease neurological symptoms." (PMID 32712869, 2021). "In addition, baicalein and baicalin were reported to increase antitumor immunity and inhibit tumor growth via the suppression of STAT3 and PD-L1 in hepatocellular carcinoma cells." (PMID 34440920, 2021). "Collectively, our observations suggest that STAT3 inhibition in tumors and tumor-surrounding microenvironment may be a promising strategy to overcome the resistance and improve therapeutic responses of PARPi treatment." (PMID 34956861, 2021). "Whether other ACEIs may also target STAT3 to exhibit their anti-tumor effects should be investigated in a future study." (PMID 33805945, 2021). "Tumor-associated dendritic cells-derived amphiregulin, a growth factor of the epidermal growth factor family, mediates an osteolytic bone metastases phenotype in lung cancer cells, accompanied by an activation of AKT and STAT3." (PMID 34064589, 2021). "Furthermore, we found that Statmp-151 has an anti-tumour effect by inhibiting the phosphorylation of Stat3." (PMID 33967793, 2021). "Although STAT3 is a well-known transcriptional activator for many genes, acetylated STAT3 also inhibits gene expression through interacting with DNA methyltransferase 1, resulting in an increase in CpG island methylation of certain tumor-suppressor genes." (PMID 34948368, 2021). "Activated-STAT3 in tumor cells not only dampens the generation of immunostimulatory mediator, but also boosts the release of the immunosuppressive factors leading to the stimulation of crosstalk between tumor cells and T cells in TME." (PMID 33957948, 2021). "STAT3 knockout mice have reduced tumor infiltrating Tregs and pronounced anti-tumor response." (PMID 34806028, 2021). "It has been reported how metformin could reduce desmoplasia of PC, reversion of epithelial-to-mesenchymal transition, and tumor-related inflammation via modulation of the AMPK/STAT3 that decreases levels of IL-1β and hampers infiltration of M2-polarized TAMs." (PMID 33477288, 2021). "Targeting STAT3 by pharmacological or genetic means led to tumor reversion as well." (PMID 33958005, 2021). "Tumour growth, as well as biomarkers of apoptosis and signalling pathways, were measured by qPCR and western blot following treatment with inhibitors of Ref-1 or STAT3." (PMID 33658640, 2021). "It is well known that inflammatory cytokines have tumor-promoting effects, mainly mediated by the activation of nuclear factor 1 B (NF1 B) and signal transducer and activator of transcription 3 (Stat3) signaling pathways, which contribute to angiogenesis and tumor cell changes." (PMID 33713207, 2021). "Thus, W2014-S effectively inhibits STAT3 signaling with potent anti-tumor activities in vitro and in vivo." (PMID 33391507, 2021). "IL-6 and IL-11 activate STAT3 through gp130, thus establishing an IL-6, IL-11/gp130/STAT3 signaling axis that prevents enterocytes from apoptosis, and facilitates cell survival and cell proliferation, ultimately promoting tumor growth." (PMID 34440220, 2021). "Rh2 could be used as a tumor energy blocker and the combination of Rh2 with an STAT3 or c-Myc inhibitor may be a promising therapeutic approach for patients with NSCLC." (PMID 34608390, 2021). "Additionally, STAT3-blocking suppressed the pro-inflammatory and the anti-inflammatory Tregs, thereby adding to T cell cytotoxicity which is conducive for the anti-tumor effects." (PMID 33957948, 2021).
tumor (continued). "Indeed, it has been found recently that elevated IL6 levels in blood plasma resulted a STAT3 hyperactivation in tumor cells." (PMID 33578642, 2021). "MDSCs could induce CSCs and promote tumor immune evasion in different kinds of cancers through CSF2/p-STAT3 signaling pathway." (PMID 34745015, 2021). "Many studies have proven that the inactivation of STAT3 attenuates key regulators participating in tumor angiogenic events like the migration of vascular cells and the sprouting of vessels, thereby enriching the tumor." (PMID 35211395, 2021). "Also, WCE rich in flavonoids suppressed IL-6, CXCL1, and CXCL8 thus reducing tumor-elicited infiltration MDSCs, TAMs, and endothelial cells accompanied by reduced STAT3 activation, in MDSCs in PC-3 and DU145 prostate cancer xenografts." (PMID 34950252, 2021). "Regarding the role of IL-17, it was shown that this pro-inflammatory cytokine secreted by Th17 cells could facilitate tumor growth in vitro and in vivo through IL-6/STAT3 pathway in HBV-related HCC19." (PMID 34045534, 2021). "IL-6 promotes NPC migration of bystander tumor cells by IL-6R/JAK/STAT3 pathway." (PMID 34165442, 2021). "Besides, VEGF and several members of the MMP family downstream of STAT3 have been proven to contribute to tumor invasion, angiogenesis, and metastasis in various cancer cells." (PMID 34638708, 2021). "In cancer, the 14-3-3ζ is substantially upregulated in various carcinomas, where it has been proposed to enhance cancer cell survival through binding of the p85 subunit of the PI3K resulting in activation of AKTs and/or by impairing tumor cell senescence in a STAT3/SKP2/p27-dependent manner." (PMID 33829040, 2021). "C-MYC-dependent downregulation of FBP1 acted as a tumor suppressor via modulating STAT3, and the C-MYC/FBP1/STAT3 axis could be a therapeutic target." (PMID 34363022, 2021). "The expression of STAT3 was primarily presented in the tumor cell nucleus of LSCC." (PMID 34941188, 2021). "Also, the STAT3 protein expression showed a reduction in the tumor tissues of the mice in sh-LINC00511 group." (PMID 34224294, 2021). "Furthermore, STAT3-mediated cytokines are well-known to regulate components of the tumor microenvironment and also mediate crosstalk between tumor cells and immune cells, including CD8+ T-cells, Tregs and NK cells." (PMID 34440920, 2021). "Similarly, STAT3 activation associated with poor survival in human PDAC and inhibition of this pathway reduced the tumor stroma and sensitized tumor-bearing mice to Gemcitabine." (PMID 34336673, 2021). "Recently, tumor patients receiving standard radiation therapy were benefited from STAT3 inhibition." (PMID 33957948, 2021). "The anti-tumor activity of fraxetin in PDA was functionally rescued by a STAT3 activator colivelin." (PMID 34320467, 2021). "In addition, STAT3 is a unique target that can redirect inflammation to promote tumour or anti-tumour activities." (PMID 34759927, 2021). "Moreover, nPD-L1 interacted with STAT3, c-Jun to govern immune-response-related genes expression and thereby modulated the anti-tumour immune response." (PMID 33139930, 2021). "Other steric antagonists have been developed, namely FLLL32, which block STAT3 dimerization and activation, and have been shown to inhibit tumor growth and angiogenesis in subcutaneous breast cancer xenograft models, however further testing of this molecule clinically has not been reported." (PMID 33805598, 2021). "Furthermore, we noted that knock-out of STAT3 decrease the proportion of phenotypes specific for tumor eradication and hybrid with anti-tumoral behavior at 33%." (PMID 34177892, 2021). "Therefore, STAT3 is overexpressed in the nucleus of tumor cells, which promotes cell proliferation and malignant transformation, hinders cell apoptosis, and exhibits carcinogenic effects." (PMID 34567204, 2021).
tumor (continued). "The increased IL-6 from MSC promotes tumor growth, STAT3 activation, and lung metastasis from OS." (PMID 34681692, 2021). "Utilizing siRNA to delete the STAT3 gene in tumor tissue could effectively overcome DC dysfunction and therefore provide a synergistic effect with tumor antigens on eliciting CTL responses." (PMID 33668746, 2021). "It plays an important role in tumor progression and aggressiveness by targeting STAT3 and PI3KR1." (PMID 34199293, 2021). "However, our study also assessed the function of the NEAT1/miR-183/STAT3 axis in the MET process in metastatic tumours." (PMID 33546665, 2021). "To determine whether MAFF-induced IL11 affects tumor cell invasion through STAT3 signaling, we first measured phospho-STAT3 protein levels." (PMID 34262028, 2021). "In NKTCL, frequent STAT3/5B activating mutations were detected in primary patient samples and cell lines, and JAK1/2/3 inhibitors potently suppressed cellular proliferation, inhibited tumor growth and induced apoptosis via abrogation of JAK/STAT program." (PMID 34680295, 2021). "This may be due to many proteins downstream of STAT3, which are crucial for tumor cell proliferation and survival were also downregulated in this process, such as c-Myc and Bcl-XL." (PMID 34760885, 2021). "However, to our knowledge only the canonical JAK2/STAT3 pathway has been implicated in OCSC function, including tumor initiation and chemoresistance." (PMID 34645505, 2021). "The loss of Erbin, a ErbB2 (v-erb-b2 avian erythroblastic leukemia viral oncogene homolog 2) interacting protein activity in cervical cancer, was reported to upsurge STAT3 phosphorylation, thus facilitating anoikis resistance and tumor invasiveness in vitro and in vivo." (PMID 33854965, 2021). "Particularly STAT3 and STAT5B are constitutively activated either by gain-of-function mutations in JAKs or other upstream oncogenes or less frequently by activating mutations and have been linked to tumour initiation and progression." (PMID 34680385, 2021). "STAT3, a key transcription factor in tumorigenesis, focuses on multiple signalling pathways, such as cell proliferation, carcinogenesis, and apoptosis, which can promote the growth, proliferation, angiogenesis, metastasis, and immune response of tumour cells." (PMID 33479376, 2021). "However, GBM-N019-targeted mTOR/CDK6/STAT3 signature, supported by a wealth of literature, contributes to tumor progressions, stemness, distant metastasis, and regulation of immune checkpoint blockade therapy outcome." (PMID 34572040, 2021). "Similarly, Bollrath J has proved that STAT3/p-STAT3 is correlated with tumor progression leading to cancer, and the high expressions of STAT3 and p-STAT3 exist in many kinds of cancers." (PMID 34165442, 2021). "Tumor tissues simultaneously up-regulate and down-regulate STAT3 activity in myeloid cells appear to be contradictory, but when time and space are taken into account, a dynamic hypothesis can be proposed." (PMID 34625124, 2021). "Additionally, treatment of nitidine chloride decreased the tumor volume through angiogenesis inhibition via reduction of STAT3 and VEGF levels in a xenograft mouse model induced by SGC-7901 cells." (PMID 34572730, 2021). "CREPT expression is positively correlated with activation of STAT3 signalling in tumours." (PMID 33531691, 2021). "Further, quercetin inhibited tumor promotion by downregulating the pro-inflammatory cytokines IL-6 and IL-10; pro-survival molecules downstream of PI3K/AKT/mTOR, Wnt/β-catenin, and STAT3 such as c-FLIPL; and molecules linked to cell proliferation, including cyclin D1 and cMyc." (PMID 34950252, 2021). "Tumor-associated fibroblasts (TAFs) mediated monocytes’ migration into tumor sites by secreting CXCL12 and induced their transformation into CD14+HLA-DR-/low MDSCs by IL-6 mediated STAT3 activation." (PMID 34680276, 2021).